NEXMIF (neurite extension and migration factor)
Description:
Involved in neurite outgrowth by regulating cell-cell adhesion via the N-cadherin signaling pathway. May act by regulating expression of protein-coding genes, such as N-cadherins and integrin beta-1 (ITGB1).
Synonyms: XPN; KIAA2022; MRX98; KIDLIA; XLID98
Tractability: PROTAC: ubiquitination databases record sites on it.
Gene: Protein-coding gene on chromosome X (74,732,856 to 74,925,472, reverse strand). Ensembl gene ENSG00000050030.
Subcellular location: Nucleus; Cytoplasm
Subcellular location (Human Protein Atlas): Nucleoplasm; Cytosol; Midbody
Gene Ontology:
Biological process: negative regulation of cell adhesion mediated by integrin; negative regulation of cell-cell adhesion mediated by cadherin; negative regulation of cell-matrix adhesion; negative regulation of neuron migration
Cellular component: nucleoplasm; nucleus; cytoplasm
Gene-disease validity (ClinGen):
ClinGen rates the evidence that NEXMIF causes each of these diseases.
X-linked complex neurodevelopmental disorder (X-linked): Definitive. A complex neurodevelopmental disorder that is transmitted via X-linked inheritance, and is characterized by intellectual disability, autism and epilepsy.
Homologues: Orthologues: chimpanzee NEXMIF (99% identical), macaque NEXMIF (98% identical), pig NEXMIF (91% identical), rabbit NEXMIF (90% identical), dog NEXMIF (90% identical), rat Nexmif (86% identical), mouse Nexmif (86% identical), guinea pig NEXMIF (85% identical), tropical clawed frog nexmif (54% identical), zebrafish nexmifb (38% identical), zebrafish nexmifa (31% identical), Drosophila melanogaster PolZ1 (9% identical), and 1 more. Paralogues in human: REV3L (19% identical), POLA1 (11% identical), POLD1 (7% identical).
Diseases named in the same sentence as NEXMIF in open-access papers:
NEXMIF is named in the same sentence as 39 diseases in open-access papers, as found by Europe PMC text mining. Sharing a sentence is not in itself a finding about the gene and the disease. The quoted sentences say what the papers report.
epilepsy (15 papers, 2016 to 2026). A brain disorder characterized by episodes of abnormally increased neuronal discharge resulting in transient episodes of sensory or motor neurological dysfunction, or psychic dysfunction. "This case contributes to the growing body of evidence linking NEXMIF variants to neurodevelopmental disorders and epilepsy, aiming to contextualize our findings within the existing literature and highlight the phenotypic variability associated with these variants." (PMID 40141841, 2025). "X-linked NEXMIF variants have been strongly associated with a broad spectrum of epilepsy." (PMID 40141841, 2025). "Finally, there are genes, such as IQSEC2, CDKL5, and NEXMIF, whose alteration causes epilepsy in both sexes." (PMID 38328757, 2023). "Several studies have demonstrated that while males with NEXMIF variants frequently present with profound ID and autistic traits, females can exhibit a range of phenotypes from mild cognitive impairment to significant neurodevelopmental deficits, often with epilepsy." (PMID 40141841, 2025). "Pathogenic NEXMIF variants are associated with autism spectrum disorder (ASD), epilepsy, strabismus, postnatal growth retardation, and microcephaly." (PMID 40141841, 2025). "Given the growing evidence of NEXMIF-associated phenotypic variability, clinicians should consider comprehensive genetic testing in patients with ASD and epilepsy, particularly those with early-onset seizures and cognitive impairment." (PMID 40141841, 2025). "Subsequent studies confirmed the role of NEXMIF variants in XLID and autism spectrum disorder (ASD), with reported phenotypes including intellectual disability (ID), epilepsy, strabismus, and other neurological or somatic features." (PMID 40141841, 2025). "Pathogenic variants in the NEXMIF gene are associated with a broad neurodevelopmental phenotype, including autism spectrum disorder (ASD), intellectual disability (ID), and epilepsy." (PMID 40141841, 2025). "NEXMIF (previously called KIAA2022) is inherited in an X-linked dominant (XLD) fashion and like other epilepsy genes is associated with a phenotypic spectrum and has been reported in both male and female patients." (PMID 37834053, 2023). "Our findings highlight the importance of recognizing epilepsy as a major feature of NEXMIF-related disorders and suggest that the c.1882C>T (p.Arg628*) pathogenic variant may be associated with a more severe phenotype in females than previously assumed." (PMID 40141841, 2025). "Our case supports the hypothesis that NEXMIF variants contribute significantly to the pathogenesis of autism spectrum disorder (ASD), intellectual disability, and epilepsy." (PMID 40141841, 2025). "NEXMIF loss of function variants have been reported in individuals with ID, ASD, and epilepsy." (PMID 38612920, 2024). "Indeed, we report for the first time post-operative seizure outcomes for six genetic causes of epilepsy: COL4A1, GRIN2B, NEXMIF, NSD1, SCN2A and SLC9A6." (PMID 37264783, 2023). "Our findings reinforce the growing recognition that NEXMIF variants contribute to a wide phenotypic spectrum, necessitating a high index of suspicion for genetic testing in patients presenting with neurodevelopmental disorders, particularly those with ASD and epilepsy." (PMID 40141841, 2025). "However, further studies are required to determine whether Jeavons syndrome represents a recurrent phenotype in NEXMIF-related epilepsy." (PMID 40141841, 2025).
epilepsy (continued). "As increased cellular and synaptic level E/I ratio in ASD can lead to increased neuronal excitability, epilepsy occurs in about 10% of people with ASD [about 15 times higher than incidence in the general population] and is particularly prevalent in individuals with NEXMIF mutations." (PMID 37965217, 2023). "Three genes remained significant when we combined all epilepsy subtypes: DEPDC5 (log[OR]=2.1, P=3.4×10−15), NEXMIF (log[OR]=4.1, P=6.3×10−9), and SCN1A (log[OR]=2.7, P=3.5×10−8)." (PMID 36865150, 2024).
Intellectual disability (10 papers, 2016 to 2026). "Based on its expression pattern in the mouse brain and association with mental retardation, NEXMIF has been suggested to have a function similar to that of ATRX, which is involved in chromatin modeling and the maintenance of genomic stability by the silencing of repetitive elements." (PMID 35970867, 2022). "We previously found that loss of the X-linked gene NEXMIF results in ASD and intellectual disability (ID)." (PMID 40606839, 2025). "Transient expression studies further support its involvement in neurite extension and neuronal circuit formation, implicating NEXMIF in the pathogenesis of intellectual disability." (PMID 40141841, 2025). "Mutations in an X-linked gene, NEXMIF (neurite extension and migration factor, also known as KIDLIA, KIAA2022, or Xpn) were first discovered in several males with ASD, intellectual disability, and other co-morbidities." (PMID 37965217, 2023).
autism (4 papers, 2016 to 2025). Persistent deficits in social interaction and communication and interaction as well as a markedly restricted repertoire of activity and interest as well as repetitive patterns of behavior. "Most other “pathogenic” and “likely pathogenic” CNVs do not overlap nor appear similar to CNVs listed in Decipher, but they do span “autism genes” listed in the SFARI GENE, and AutismKB databases, such as DMD, NEXMIF, NLGN4X, PRKN, and others." (PMID 35762097, 2022). "However, a whole NEXMIF duplication, leading to reduced expression, has been reported in a family with XLID and autism." (PMID 32715656, 2020).
Anxiety (2 papers, 2023 to 2025). Intense feelings of nervousness, tension, or panic often arise in response to interpersonal stresses. "Taken together, these results demonstrate that postnatal NEXMIF overexpression can lead to the presence of hyperactivity and anxiety-like behaviors in mice." (PMID 40606839, 2025). "Because ASD is often co-morbid with attention-deficit/hyperactivity disorder (ADHD) and anxiety disorder, we next sought to determine the effects of NEXMIF overexpression on hyperactivity and anxiety-like phenotypes in NEXOX mice." (PMID 40606839, 2025). "Our previous work has shown that in an open-field task, NEXMIF KO mice are more active than WT mice, reflecting higher levels of anxiety in NEXMIF KO mice." (PMID 37965217, 2023). "We report that NEXMIF overexpression in mice led to impaired communication, short-term memory deficits, reduced social behavior, hyperactivity, repetitive/restrictive behaviors, anxiety-like behavior, and altered nociception at adolescent ages, accompanied by attenuated dendritic spine density." (PMID 40606839, 2025).
epileptic syndromes (2 papers, 2025). "Our analysis suggests that NEXMIF variants may contribute to a broader spectrum of epileptic syndromes, including photosensitive epilepsy such as Jeavons syndrome." (PMID 40141841, 2025). "Further research is needed to clarify the molecular mechanisms linking NEXMIF dysfunction to epileptic syndromes and neurodevelopmental disorders." (PMID 40141841, 2025). "However, the role of NEXMIF in specific epileptic syndromes remains insufficiently explored." (PMID 40141841, 2025).
Jeavons syndrome (2 papers, 2025). "This study expands the current knowledge on NEXMIF variants by providing one of the first documented cases of Jeavons syndrome associated with a pathogenic NEXMIF variant." (PMID 40141841, 2025). "Given its involvement in generalized epileptic encephalopathies, NEXMIF dysfunction may contribute to the broader spectrum of these disorders, including Jeavons syndrome." (PMID 40141841, 2025).
X-linked intellectual disability (2 papers, 2016 to 2025). An X-linked intellectual deficiency in which not enough information is known, reported or published to indicate whether a gene causes non-syndromic or syndromic presentations. "The study reported two males with severe X-linked intellectual disability (XLID), while a carrier female remained asymptomatic, suggesting that the loss of NEXMIF function leads to a severe phenotype in hemizygous males." (PMID 40141841, 2025).
allergies (1 paper, 2022). "The possible association of severe allergies, anaphylaxis, and autoimmune problems and NEXMIF pathogenic variants warrants further investigation." (PMID 35146903, 2022).
diabetes (1 paper, 2022). "During our study, we identified a female with non-autoimmune diabetes and learning disabilities who was carrying a NEXMIF variant, underlining a role for NEXMIF in the development of diabetes." (PMID 35970867, 2022). "From these patients, one additional female has been described to have diabetes, suggesting that NEXMIF plays a role in diabetes development." (PMID 35970867, 2022).
Dravet syndrome (1 paper, 2025). "Eight individuals (6.2%) had died after their last follow-up; four had SCN1A-related Dravet syndrome; the others had CHD2, GNAO1, KCNT1 and NEXMIF-related DEEs." (PMID 39882024, 2025).
Encephalopathy (1 paper, 2025). Encephalopathy is a term that means brain disease, damage, or malfunction. "The identification of a rare NEXMIF pathogenic variant (c.1882C>T; p.Arg628*) in our patient, combined with a detailed review of the literature, expands the current understanding of NEXMIF-related encephalopathy and its associated phenotypic variability." (PMID 40141841, 2025).
infertile (1 paper, 2023). "Since NEXMIF is an X-linked gene and NEXMIF KO male mice are infertile, homogenous female mice cannot be generated." (PMID 37965217, 2023).
cancer (3 papers, 2016 to 2020). A tumor composed of atypical neoplastic, often pleomorphic cells that invade other tissues. "The neurite extension and migration factor (NEXMIF) gene has not been previously reported in cancer, thus its function is unknown." (PMID 30940089, 2019).
neurodevelopmental disorder (2 papers, 2020 to 2025). A behavioral and cognitive disorder with onset during the developmental period that involves impaired or aberrant development of intellectual, motor, or social functions. "Pathogenic variants in the NEXMIF gene have been increasingly recognized as a cause of neurodevelopmental disorders, with variable expressivity depending on the specific variant, the sex of the individual, and potential modifying genetic or environmental factors." (PMID 40141841, 2025). "Pathogenic variants in the NEXMIF gene, formerly known as KIAA2022, XLID98, or XPN, have been identified as a cause of X-linked intellectual disability 98 (XLID98), a neurodevelopmental disorder with a complex phenotypic spectrum." (PMID 40141841, 2025). "Further research is needed to elucidate the precise molecular mechanisms by which NEXMIF dysfunction contributes to neurodevelopmental disorders." (PMID 40141841, 2025).
NEXMIF also shares sentences with these, for which no sentence is quoted: Angelman syndrome (2 papers); autism spectrum disorder (2); cognitive deficits (2); colorectal cancer (2); developmental delay (2); Strabismus (2); Alzheimer disease (1); anaphylaxis (1); anxiety disorder (1); aortic stenosis (1); breast carcinoma (1); colon tumor (1); Doose syndrome (1); EARS disease (1); gastric adenocarcinoma (1); gastric cancer (1); gastroesophageal reflux (1); hematological malignancies (1); infection (1); learning disabilities (1); neuronal migration disorders (1); photosensitive epilepsy (1); schizophrenia (1); Tetralogy of Fallot (1); tumor (1).